MIR3529 (microRNA 3529)
Synonyms: hsa-mir-3529; mir-3529
Gene: MicroRNA gene on chromosome 15 (88,611,847 to 88,611,924, reverse strand). Ensembl gene ENSG00000283484.
Gene Ontology:
Biological process: miRNA-mediated post-transcriptional gene silencing
Cellular component: RISC complex
Homologues: Orthologues: chimpanzee MIR3529 (100% identical).